BRAF (B-Raf proto-oncogene, serine/threonine kinase)
Diseases named in the same sentence as BRAF in open-access papers (continued):
Sharing a sentence is not in itself a finding about the gene and the disease.
adenocarcinoma (continued). "Compared to patients with non‐BRAF mutation, patients with BRAF mutations were associated with adenocarcinomas (89.3% vs. 70.6%, P = 0.048) and never smokers (78.6% vs. 56.7%, P = 0.019)." (PMID 28135039, 2017). "Considering the adenocarcinomas without any actionable EGFR or BRAF mutations, the percentage of tumors exhibiting MET exon 14 splice mutations was eight out of 100 patients." (PMID 28418914, 2017). "These patients may benefit from EGFR TKIs and BRAF inhibitors like other NSCLCs, especially adenocarcinomas." (PMID 28638113, 2017). "Therefore, we analyzed two NSCLC adenocarcinoma cell lines harboring two different mutations along the P-loop of the BRAF kinase domain and a CRC cell line of adenocarcinoma origin with a BRAF mutation positioned within the DFG motif." (PMID 28947956, 2017). "BRAF mutation is associated with adenocarcinoma, and BRAF V600E mutation is more likely in never smokers." (PMID 28135039, 2017). "BRAF mutations in this cohort were not confined to samples displaying adenocarcinoma histology but were also found in two SCC cases." (PMID 26208325, 2015). "BRAF mutations in NSCLC were significantly associated with adenocarcinomas (ADCs) (compared with non-ADCs, OR = 4.96, 95%CI = 2.29–10.75)." (PMID 24979348, 2014). "KRAS and BRAF mutations were observed in 45% and 33% of serrated adenocarcinomas and in 27% and 0% of non-serrated CRCs (P < 0.001)." (PMID 21457162, 2011). "The present study aimed to investigate the relationship between BRAF and K-ras mutations in 186 adenocarcinomas from the EPIC Norfolk cohort and clinicopathological features, lifestyle and dietary factors." (PMID 20233436, 2010). "These mutations consisted of 19 KRAS (24.7%), 10 EGFR (13%), five BRAF (6.5%), four PIK3CA (5.2%), one HER2 (1.3%), one HER4 (2.2%) and none for HER3. mEGFR, mBRAF and mHER2 were present exclusively in adenocarcinomas while mKRAS were more frequent in adenocarcinoma and large cell histologies." (PMID 19238210, 2009). "Adenocarcinoma cases had a higher prevalence of SNVs, CNVs, and/or fusions/rearrangements in 28 genes including therapy-associated genes such as KRAS (37.5% vs 4.6%), EGFR (17.1% vs 1.3%), BRAF (5.2% vs 1%), ERBB2 (1.8% vs 0.8%), RET (0.9% vs 0.3%), and ROS1 (1.2% vs 0.1%)." (PMID 39664186, 2024). "In addition, 96.2% of the patients had adenocarcinoma, and most (96.2%) received first-line therapy (23.5% anti-BRAF), with a progression-free survival (PFS) and overall survival (OS) of 10.0 [95% confidence interval (CI): 1.5–36.0 months] and 24.0 months [95% CI: 3.0–53.0 months], respectively." (PMID 35814395, 2022). "BRAF mutation is more likely to be associated with adenocarcinoma and never smokers." (PMID 28135039, 2017). "Several biomarker-guided therapies have been approved, targeting genes frequently altered in adenocarcinoma, such as EGFR, BRAF, MET, ALK, ROS1, RET and NTRK." (PMID 39199558, 2024). "She underwent Hartmann surgery in January 2019 (pT3N0M1, stage IV, adenocarcinoma [tub2], RAS mutant, BRAF WT), and started leucovorin simple therapy with 5FU in March 2019." (PMID 37608127, 2024). "Due to ascending colon cancer and lung metastasis (pT3N0M1, stage IV, adenocarcinoma [tub1], RAS mutant, BRAF wild type [WT]), he underwent right hemisection in 2019." (PMID 37608127, 2024). "In some NSCLC patients, mainly adenocarcinoma, molecular alterations in driver genes, like EGFR, KRAS, HER2, ALK, MET, BRAF, RET,ROS1, and NTRK are recognized." (PMID 37346803, 2023). "Sakamoto T proposed that BRAF V600E was tested positive by immunostaining (anti-BRAF V600E rabbit monoclonal antibody clones) and NGS in both adenocarcinoma and LCNEC part." (PMID 36507119, 2022).
adenocarcinoma (continued). "A number of adenocarcinoma-specific gene alterations are known, including EGFR, KRAS and BRAF, and these affect the gene products of the MAP kinase and PI3/AKT signaling pathways." (PMID 25364428, 2014). "From December 2014 to July 2019, 11 patients with BRAF-V600E-mutation NSCLC were included in the MATCH-R study, all diagnosed with adenocarcinoma and negative for EGFR, ALK, ROS1, KRAS, and HER2." (PMID 39529955, 2024). "It is also conceivable that DARPP-32 might contribute to TKI therapy-refractory growth in adenocarcinomas in which additional downstream genetic alterations exist in genes like RET, ALK, BRAF, or KRAS, although such studies are yet to be conducted." (PMID 34675407, 2022). "Other examples of carcinogenic drivers for adenocarcinoma include modifications in protein kinase B (AKT), BRAF, human epidermal growth factor receptor-2 (HER2), phosphatidylinositol-4,5-bisphosphate 3-kinase catalytic subunit alpha (PIK3CA), MET, ROS1, RET, and KRAS." (PMID 35004079, 2022). "A study was performed with a customized NGS panel (called SiRe) including six genes [EGFR, KRAS, NRAS (NRAS Proto-Oncogene, GTPase), BRAF, KIT Proto-Oncogene Receptor Tyrosine Kinase (KIT)), Platelet-Derived Growth Factor Receptor Alpha (PDGFRA)] for 194 patients with advanced adenocarcinomas." (PMID 33922637, 2021). "According to the literature, 10–13% of Caucasian patients with adenocarcinoma (which represents the most part of non-squamous NSCLC) presents an EGFR activating mutation, 2–7% rearrangements of ALK and 1–4% BRAF mutations." (PMID 34885238, 2021). "We did not detect mutations of the BRAF, APC, or SMAD4 genes in the adenocarcinomas, although these genes have been reported as frequently mutated in previous studies." (PMID 34422662, 2021). "VAMP2-NRG1 was reported in a 67-year-old never-smoker woman with adenocarcinoma with no mutation in EGFR, KRAS and BRAF and with no fusion genes involving ALK, ROS1 or RET." (PMID 27626312, 2016). "Biologically, these adenocarcinomas differ greatly from adenocarcinomas seen in ever smokers, with differences in the proportion of oncogenic driver mutations such as EGFR, KRAS, and BRAF; these seem to predominate in never smokers, females, and those of east Asian descent." (PMID 39125735, 2024). "In total, putative actionable genomic targets (FGFR2, BRAF-V600E, MTOR, NRAS, and KDM6A) were identified in 35% of the cases by OncoKB search, an important finding given the high number of fluent transitions from high-grade IEN to adenocarcinoma at the time of diagnosis (14/17 cases)." (PMID 34205964, 2021). "In a subgroup of non-smokers with adenocarcinoma, EGFR was the most frequently altered gene, with a mutation rate of 49.8%, followed by EML4-ALK (9.3%), PTEN (9.1%), PIK3CA (5.2%), c-Met (4.8%), KRAS (4.5%), STK11 (2.7%), and BRAF (1.9%)." (PMID 22768234, 2012). "Thus, it is conceivable that patients carrying BRAF mutations could be eligible to receive TKI treatments, even in the absence of an adenocarcinoma component." (PMID 33260892, 2020). "As there is no NSCLC cell line with a BRAF mutation in the DFG motif, we included a CRC cell line of adenocarcinoma origin harboring a BRAF mutation along this motif, although we are aware that the significance of BRAF mutations and their inhibition might be context dependent." (PMID 28947956, 2017). "In our investigated cohort of triple-negative NSCLCs (EGFR, KRAS, and BRAF mutation negative) the number of cases with either ROS1 or RET fusions were similar to that of ALK-positive cases, supporting the need of multiplexed gene fusion diagnostics in NSCLC and adenocarcinoma specifically." (PMID 28415793, 2017). "The histopathology demonstrated a low-grade adenocarcinoma MMR proficient, BRAF V600E wildtype, with no microsatellite instability." (PMID 40734778, 2025).
adenocarcinoma (continued). "The adenocarcinoma showed expression of CK20 and CA19-9 but no expression of CA125, CA153, CK7 or BRAF." (PMID 29029440, 2017). "Biopsy of the right supraclavicular lymph node revealed lung tissue adenocarcinoma and negative Kirsten rat sarcoma viral oncogene homolog (K-Ras), epidermal growth factor receptor (EGFR), B-raf proto-oncogene (BRAF), C-ros oncogene 1 (ROS1), and anaplastic lymphoma kinase (ALK) rearrangement." (PMID 33728131, 2021).
CNS tumors (48 papers, 2012 to 2026). "The therapeutic targeting of the MAPK signaling pathway has clinical benefits in various CNS tumors, particularly in pLGGs that express the BRAF V600E mutation." (PMID 41514664, 2026). "Only a subset of pediatric CNS tumors will harbor canonical driver mutations (e.g. in Histone 3, BRAF, NTRK, SMARCB1) and the catalog of prognostic molecular findings is constantly evolving." (PMID 39834946, 2024). "Dabrafenib combined with trametinib is currently considered the standard of care in progressive BRAF V600E-mutated CNS tumours." (PMID 39272879, 2024). "For example, the role of driver mutations, such as BRAF and its effect on pathogenesis of CNS tumors, has recently gained special interest." (PMID 35130969, 2022). "This series describes three patients from two neurosurgical centers in Ireland with BRAF V600E-mutated CNS tumors." (PMID 36619621, 2022). "This series describes the cases of three patients with BRAF V600-mutated CNS tumors in whom BRAF-targeted therapy was utilized, including one of the first reported cases of response to targeted therapy in BRAF V600E-mutated RDD." (PMID 36619621, 2022). "This series contributes to the limited published data on targeted therapy in BRAF-mutated CNS tumors and includes an exceptional case describing the response to BRAF inhibitor therapy in BRAF-mutated RDD." (PMID 36619621, 2022). "Class I mutations constitute 44% of all BRAF mutations in CNS tumors and are associated with a point mutation of the BRAF gene." (PMID 36686797, 2022). "BRAF V600E mutations can be found in CNS tumors in any location, and are often detected in midline tumors, including the optic pathway, brainstem, and spinal cord." (PMID 33673070, 2021). "BRAF alterations are identifiable using current diagnostic techniques, and at present play an important role in the pathologic workup of CNS tumors and to a lesser degree in PNS." (PMID 33042847, 2020). "This review discusses the prevalence of BRAF alteration within select notable CNS tumors, and their prognostic associations." (PMID 33042847, 2020). "We have clearly shown that both early and late stage autophagy inhibition are effective in autophagy dependent CNS tumors, such as those with BRAF mutations." (PMID 32457939, 2020). "Because BRAF mutation is generally more common in pediatric CNS tumors, than in adult cases the strategy of targeting autophagy holds promise in this group." (PMID 30443293, 2018). "CNS tumor cells with the BRAF V600E mutation have higher rates of autophagy in response to cell stress than those without." (PMID 30443293, 2018). "Because of the therapeutic implications, the relevance of detecting BRAF mutation is already expanding to other types of CNS tumors, therefore requiring robust detection techniques." (PMID 28293477, 2017). "In another cohort study of over 1,300 CNS tumors, 66.7% of PXAs, 18% of GGs, and 9% of extra-cerebellar PAs harbored the BRAF V600E mutation." (PMID 25785246, 2015). "A complete response of a CNS tumor to BRAF inhibitor therapy underscores the need to fully investigate these targeted drugs in patients with CNS tumors which harbor BRAF mutations." (PMID 24725538, 2014). "The clinicopathologic diversity of BRAFV600E-mutated CNS tumors due to diverse co-occurring alterations makes treatment decisions ambiguous and raises the need for preclinical testing of combination therapies of BRAF/MEK inhibitors and therapies targeting co-occurring alterations." (PMID 37920169, 2023). "Therefore, it seems now clear that the diagnosis of CNS tumors should include molecular testing for BRAF mutations or fusions, and, if present, patients ought to be considered for targeted treatment." (PMID 32879641, 2020).
CNS tumors (continued). "Simultaneously, we decided to verify whether the combination of fully automated tests—BRAF-VE1 immunohistochemistry (IHC) and Idylla BRAF mutation assay—may be useful to accurately predict it in the case of specified CNS tumors." (PMID 32879641, 2020). "Moreover, the response of CNS tumors with alternative BRAF abnormalities, such as alternate V600 mutations or fusions, will also need to be investigated." (PMID 24725538, 2014). "The highest incidence of CNS tumors that harbor BRAF V600E-mutations occurs in pediatric patients." (PMID 24725538, 2014). "Currently, only BRAF pV600E evaluation for recurrent or progressive CNS tumors has been proved useful as a clinical standard for therapy selection." (PMID 41567539, 2025). "It was evaluated in the phase I/IIa trial of previously treated BRAF-altered advanced solid and CNS tumors." (PMID 38203795, 2024). "BRAF missense mutations have been identified in these PDX by molecular profiling, but due to the relative scarcity of BRAFV600E altered CNS tumors amongst brain tumor patients, PDX for these tumors are rare." (PMID 37920169, 2023). "The well-described KIAA1549::BRAF fusion was most frequently observed, being identified in 13/23 (57%) CNS tumors with a clinically significant finding." (PMID 37686670, 2023). "Alterations in the BRAF gene, which encodes a central kinase in the MAPK signaling pathway, are prevalent in CNS tumors and are enriched in the pediatric population." (PMID 37920169, 2023). "Further molecular stratification and clinical trial design are required for the treatment of pediatric CNS tumors with BRAF and MEK inhibitors." (PMID 36077798, 2022). "As we improve our knowledge of pediatric CNS tumors, the BRAF pathways are receiving growing attention from the scientific community." (PMID 36077798, 2022). "We also have demonstrated in vitro, ex vivo, and in patients that autophagy inhibition overcomes multiple molecularly distinct resistance mechanisms to BRAF inhibition in BRAF mutant CNS tumors." (PMID 32457939, 2020). "As more specific and optimized autophagy inhibitors are being developed, future studies will directly compare early and late stage autophagy inhibition to determine optimal targets in autophagy dependent BRAF mutant CNS tumors." (PMID 32457939, 2020). "Based on our results and those reported by other groups, it seems that strong-to-moderate staining for the VE1 antibody in CNS tumors equates with the positive results of BRAF V600E molecular testing." (PMID 32879641, 2020). "In CNS tumors, the most common targetable lesions were BRAF fusions (with KIAA1540 and other partners) that retained the active BRAF kinase domain, amenable to MAPK targeting with MEK inhibitors." (PMID 31133068, 2019). "In other studies, small numbers of BRAF mutations were identified in primary CNS tumors using sequencing methods that were not identified on IHC." (PMID 36619621, 2022). "BRAF alterations have been largely described in both pediatric and adult primary CNS tumors." (PMID 36686797, 2022). "The authors also demonstrated that chloroquine could improve vemurafenib sensitivity in children with ganglioglioma, indicating that pediatric CNS tumors with BRAF (V600E) are autophagy-dependent and should be targeted with autophagy inhibition in combination with other therapeutic strategies." (PMID 36197606, 2022). "In tumors with priority level 1 targets, several known actionable targets such as ALK, BRAF and NTRK were detected in extracranial solid and CNS tumors." (PMID 38357207, 2024). "Although encorafenib features a longer dissociation half-life from BRAF V600E and potentially better pharmacodynamic suppression of MAPK signaling, its efficacy in CNS tumors may be limited by its lower BBB penetration." (PMID 41514664, 2026).
CNS tumors (continued). "The SACHA French prospective observational study (2020 to 2022) assessed the off-label or compassionate use of targeted drugs and demonstrated that certain targeted drugs, such as BRAF or MEK inhibitors, are among the most frequently utilized, with pediatric CNS tumors being the main indication." (PMID 39409964, 2024). "BRAF and MEK inhibitors may, in the future, significantly reduce the need for classic chemotherapy and radiation therapy in treating pediatric CNS tumors." (PMID 36077798, 2022). "Like other primary CNS tumors, molecular characterization is important for the prognosis at the moment of the diagnosis, but the WHO classification system has not yet officially described PXA BRAF mutated and BRAF wild-type as distinct clinical entities." (PMID 36077798, 2022). "BRAF V600E mutations typically do not occur in GBM cases, whereas one study observed such mutations were more prominent in PXAs and aPXAs in relation to other CNS tumors in adults and children." (PMID 33963808, 2021). "However, our genotype–phenotype integrated diagnoses based on the 2021 WHO classification of CNS tumors were not as relevant to the genotypes as neuroimaging features; the most frequent diagnosis was MAPK pathway-altered dLGG in both BRAF V600E and FGFR1 mutations." (PMID 39081340, 2024).